TIMP2 (TIMP metallopeptidase inhibitor 2)
Diseases named in the same sentence as TIMP2 in open-access papers (continued):
Sharing a sentence is not in itself a finding about the gene and the disease.
glaucoma (10 papers, 2008 to 2025). Increased pressure in the eyeball due to obstruction of the outflow of aqueous humor. "Furthermore, the presence of preoperative glaucoma was associated with higher levels of TIMP2 and MMP2." (PMID 41009516, 2025). "The TIMP-2 levels were significantly elevated in both glaucoma (POAG and PEXG) and PES subjects, while MMP-2 was higher in PEXG and PES subjects, when compared to samples from controls." (PMID 34439995, 2021). "In addition, the TIMP-2 level was also found to be elevated in the aqueous humor of patients with primary open-angle glaucoma compared to the cataract controls." (PMID 35457074, 2022). "Increased levels of MMP-2, CTGF, and TIMP-2 were observed in 60 glaucoma patients (30 PEXG and 30 POAG) when compared to controls, which may involve changes during the pathogenesis of the disease." (PMID 34439995, 2021). "Upregulation of TIMP2 and other TIMP species has been found in several forms of glaucoma as well and will promote ECM accumulation." (PMID 38990974, 2024). "They found that MMP2, MMP3, TIMP1, and TIMP2 were detected at significantly higher concentrations in aqueous samples from eyes with pseudoexfoliation with and without glaucoma compared with cataractous eyes." (PMID 41009516, 2025). "Among the identified proteins significantly altered in glaucoma, eight were further studied using semi-targeted or targeted approaches, showing higher levels of ALB, APOC3, CysC, TIMP2, A2M, PGTDS, and ENPP2, and lower levels of SOD1, in POAG patients compared to control subjects." (PMID 34439995, 2021). "The increase in TIMP1 and TIMP2 may lead to the inhibition of MMP2 activity and contribute to the IOP of primary open-angle glaucoma." (PMID 33195434, 2020). "Higher levels were revealed in the aqueous humor of subjects with acute primary angle-closure but significantly lower levels were noted in aqueous samples in subjects with primary open-angle glaucoma compared to control cataract patients, with no change in TIMP-2 levels." (PMID 35457074, 2022). "Interestingly, these findings may indicate that MMP-2 expression is not independent, and imbalances in the MMP-2/TIMP-2 ratio may be significant in the pathogenesis of ocular hypertension in glaucoma." (PMID 35457074, 2022).
neuroblastoma (10 papers, 2005 to 2024). Neuroblastoma (NB) is the most common solid, extracranial childhood tumor. "Increased MMP-2 expression, in addition to decreased TIMP-2 expression, had a significant association with more advanced stages, and therefore, could possibly serve as a prognostic factor in patients with neuroblastoma." (PMID 32751899, 2020). "In order to obtain the optimal results, multivariate COX regression analysis was performed on 6 key-target genes, and 3 genes associated with neuroblastoma were identified, i.e., BIRC5, TIMP2 and CASP9." (PMID 38982456, 2024). "In neuroblastoma, TIMP-2 was overexpressed in the less aggressive 007 line compared with expression in the WAC-2 cell line." (PMID 32751899, 2020). "Interestingly, treatment of human neuroblastoma cells with the DNA methyltransferase inhibitor 5-azacytidine (5-AzaC) restored TIMP-2 expression and resulted in a reduction of in vitro invasiveness." (PMID 15918904, 2005). "In vitro studies verified puerarin's impact on BIRC5, TIMP2, and CASP9 expression, inhibiting proliferation in neuroblastoma SH-SY5Y cells." (PMID 38982456, 2024). "Advanced stages of neuroblastoma show increased expression of the matrix metalloproteinase (MMP-2), and a higher MMP-2 to TIMP-2 ratio has been shown to correlate with poorer prognosis for neuroblastoma patients." (PMID 23446555, 2013). "Besides, multivariate COX regression analysis was carried out to obtain three genes related to the prognosis of neuroblastoma, namely BIRC5, TIMP2 and CASP9." (PMID 38982456, 2024). "Our main objective in this study was to evaluate the effectiveness of NM on neuroblastoma cells in vivo using the nude mouse xenograft model and in vitro, evaluating the effect of NM on cell viability, MMP-2 and -9 secretion, TIMP-2 secretion, Matrigel invasion and cellular apoptosis and morphology." (PMID 23446555, 2013). "To explore the possibility that MYCN might be directly binding to the TIMP2 promoter and directly repressing transcription, we examined previously published genome-wide MYCN binding site data for neuroblastoma." (PMID 22662276, 2012). "Expression of angiogenin, TIMP1, and TIMP2 was specifically elevated in the PRL3-positive tumor specimens but not in PRL3-negative adjacent normal tissues, with normalized net expression of these angiogenic factors increased in neuroblastoma, leiomyosarcoma, and rhabdomyosarcoma tumors." (PMID 37674627, 2023).
pulmonary fibrosis (10 papers, 2012 to 2026). Chronic progressive interstitial lung disorder characterized by the replacement of the lung tissue by connective tissue, leading to progressive dyspnea, respiratory failure, or right heart failure. "In this study, we aim to investigate the in vivo and in vitro roles of GSK-3 inhibition in the modulation of MMP-9 and MMP-2 and of their inhibitors TIMP-1 and TIMP-2 in the development of lung fibrosis." (PMID 34235177, 2021). "In the present study, it was observed that the ITC regulates the expression of the MMP-15 and TIMP-2 genes that have been recognized as inducers of pulmonary fibrosis." (PMID 29040281, 2017). "TIMP-1 and TIMP-2 are expressed by a variety of cell types, and are known to play a major role in regulating pulmonary fibrosis." (PMID 22911824, 2012). "The increased expression of TIMP-2 in bleomycin-induced pulmonary fibrosis has also been reported." (PMID 34235177, 2021). "Adrenergic-stimulated histological lung fibrosis is associated with a remarkable increase in TGFβ1, collagen I, MMP-2 and TIMP-2 mRNA expression, suggesting a link between adrenergic stimulation, the up-regulation of ECM molecules and the promotion of fibrotic processes." (PMID 34071777, 2021). "In the ACE2-uMSC group, the MMP-2/TIMP-2 ratio was relatively balanced, which may have promoted the protection of injury-induced pulmonary fibrosis." (PMID 25435005, 2015). "Depletion of neutrophils might attenuate lung fibrosis and inflammation through down-regulating TGF-β1, TNF-α, IL-17, MMP-8 and TIMP-2." (PMID 27690127, 2016). "Our data agrees with a study in human lung fibrosis, where TIMP1 mRNA was markedly increased in response to lung injury, whereas there was no change in TIMP2 mRNA levels." (PMID 36032279, 2022).
renal cell carcinoma (10 papers, 2006 to 2025). "In the present study, mean MMP-2, MMP-9, MT1-MMP, TIMP-1, and TIMP-2 mRNA expression in the renal cell carcinomas was significantly higher than in the normal renal tissue (P <0.05)." (PMID 23281640, 2013). "In summary, mean MMP-2, MMP-9, MT1-MMP, TIMP-1, and TIMP-2 mRNA expression in the renal cell carcinomas was significantly higher than in the normal renal tissue (P <0.05)." (PMID 23281640, 2013). "Mean MMP-2, MMP-9, MT1-MMP, TIMP-1, and TIMP-2 mRNA expression in the renal cell carcinomas was significantly higher than in the normal renal tissue." (PMID 23281640, 2013). "Mean MMP-2, MMP-9, MT1-MMP, TIMP-1, and TIMP-2 mRNA expression in the renal cell carcinomas was significantly higher than in the normal renal tissue (P <0.05)." (PMID 23281640, 2013). "In this study, we examined the expression of MMP-2, MMP-9, membrane-type 1 (MT1)-MMP, TIMP-1, and TIMP-2 in renal tissue samples of renal cell cancer and examined the correlation between their expression and clinicopathological parameters." (PMID 23281640, 2013). "In the present study, we examined the expression of MMP-2, MMP-9, MT1-MMP, TIMP-1, and TIMP-2 mRNA in human renal cell carcinoma tissues by a reverse transcriptase-polymerase chain reaction (RT-PCR) assay and examined the correlation between their expression and clinicopathological parameters." (PMID 23281640, 2013). "Furthermore, TIMP-1 and TIMP-2 expression by immunohistochemistry has been found to be significantly correlated with poor prognosis in renal cell carcinoma." (PMID 23281640, 2013). "Concerning renal cell carcinoma (RCC), TIMP2 is inversely correlated with markers of tumour progression." (PMID 34781885, 2021). "In human renal cell carcinoma cell lines, Tiam1 inhibits invasion through Rac-induced upregulation of tissue inhibitor of metalloproteinases-1 (TIMP-1) and TIMP-2." (PMID 24069171, 2013). "Studies in renal cell carcinoma (RCC) xenograft models have shown that inhibition of miR-193a-5p levels in tumor-associated macrophage (TAM) exosomes can inhibit tumor progression and metastasis by inhibiting angiogenic mimicry (VM) and upregulating TIMP2 expression." (PMID 40161373, 2025). "Adiponectin, via AdipoR1, inhibits mTOR through AMPK activation in renal cell carcinoma (RCC), suppresses vascular endothelial growth factor (VEGF), MMP-2 and MMP-9 and increases TIMP-1 and TIMP-2 secretion, resulting in decreased growth, dissemination and angiogenesis of RCC." (PMID 37686525, 2023). "In terms of pathologic grade of renal cell carcinoma, the differences in MMP-2, MMP-9, MT1-MMP, TIMP-1, and TIMP-2 mRNA expression levels were not significant." (PMID 23281640, 2013).
Alzheimer disease (8 papers, 2014 to 2024). A progressive, neurodegenerative disease characterized by loss of function and death of nerve cells in several areas of the brain leading to loss of cognitive function such as memory and language. "On the other hand, the TIMP-2 rs7503726 AA genotype was inversely correlated with Alzheimer’s disease susceptibility, and the presence of minor alleles of rs7503726 (A allele) had protective effects against Alzheimer’s disease." (PMID 36232390, 2022). "Two of the studied proteins, MMP-10 and TIMP-2, differed between the patients with Alzheimer’s disease and the controls." (PMID 37221606, 2023). "TIMP2 levels are elevated in a variety of CNS diseases, including multiple sclerosis, Alzheimer’s disease, and Huntington’s disease." (PMID 38015626, 2023). "Conversely, TIMP-2 was significantly increased in the serum or cerebrospinal fluid of multiple sclerosis (MS), stroke, Alzheimer’s disease (AD), and Huntington’s disease (HD) patients, suggesting a protective role for TIMP-2 in these diseases." (PMID 24970341, 2014).
breast tumor (8 papers, 2008 to 2025). "In breast tumor, cancer cells delivered exosomal miR-4443 to stromal cells of the primary tumor and impaired TIMP2 to promote liver metastasis." (PMID 37143656, 2023). "More recently, we demonstrated that stromal POSTN distribution in metastatic breast tumors of the lung is dramatically altered following TIMP2 treatment." (PMID 31882975, 2019). "On the other hand, high levels of TIMP-2 have also been correlated with distant metastasis of breast tumors." (PMID 18474097, 2008). "The half‐lives of metastasis‐suppressing mRNAs, including MTSS1, TIMP2, RB1, and PTEN, were prolonged by approximately 1‐fold in Arid4a‐overexpressing breast tumor cells." (PMID 40066676, 2025). "With regards to TIMP2:MMP expression, breast tumors seemed to be more consistent with an almost ubiquitous increase in MMP11 and a smaller number of patients exhibiting high MMP9 expression." (PMID 31882975, 2019). "Notably, the expression of metastasis‐suppressing genes, including MTSS1, TIMP2, Rb1, and PTEN, was increased according to the expression of Arid4a in breast tumor tissues." (PMID 40066676, 2025). "MTSS1, TIMP2, RB1, and PTEN were selected as targets of Arid4a in breast tumor cells for further study for two main reasons: (i) they are among the genes most highly regulated by Arid4a in breast tumor cells; and (ii) they are known typical metastasis inhibitory genes." (PMID 40066676, 2025).
endometrial cancer (8 papers, 2007 to 2024). Primary or metastatic malignant neoplasm involving the endometrium (mucous membrane that lines the endometrial cavity). "High expression of MMP-2 in combination with low expression of TIMP2 represents a high risk for local and distant metastasis of endometrial cancer." (PMID 36982551, 2023). "However, the two other genes, RUNX1 and TIMP2, which are common in cervical, ovarian, and endometrial cancers, have 5% mutation for amplification and deletion." (PMID 31205821, 2019). "An increasing expression of MMP-2 and decreasing expression of TIMP-2 in endometrial carcinoma tissue correlates with the histological grade of endometrial carcinoma." (PMID 34830354, 2021). "Expession analysis of TIMPs, including TIMP-2, remains to be done however in our endometrial cancer cell lines." (PMID 20942921, 2010). "The level expression of MMP-2, MMP-14 and TIMP-2 in EN-1078D cell line is consistent with an endometrial cancer with high invasive potential." (PMID 17894888, 2007). "In some studies, it was found that in endometrial cancer, a high expression of MMP-2 and a low expression of TIMP-2 are important tumor markers." (PMID 38255200, 2024). "In endometrial cancer, a high expression of MMP-2 and low expression of TIMP-2 seem to be potent markers for tumors, which provide a high risk of local and distant metastasis." (PMID 20942921, 2010).
endometriosis (8 papers, 2013 to 2023). The growth of functional endometrial tissue in anatomic sites outside the uterine body. "Another study showed that MMP2 and TIMP2 were associated with advanced-stage endometriosis." (PMID 34827737, 2021). "Another study showed up-regulation of MMP-2 activity by tissue inhibitor of metalloproteinases 2 (TIMP-2) in early endometriosis and an inhibitory effect of curcumin on endometriosis." (PMID 37375677, 2023). "Previous studies have reported higher levels of MMP-2 expression and lower mRNA levels for TIMP-2 in eutopic tissues of endometriosis patients relative to the endometrium from control groups." (PMID 31037923, 2019). "The reduced expression of TIMP-2 indicated attenuated inhibition on MMP-2 activity, however it also suggested that limited TIMP-2 and increased MT1MMP expressions are associated with increased MMP-2 activation during the progression of endometriosis." (PMID 27695098, 2016). "In addition, increased MT1MMP and decreased tissue inhibitors of metalloproteinases (TIMP)-2 expressions were found in the late stages of endometriosis indicating more MMP-2 activation with disease progression." (PMID 27695098, 2016). "In order to clarify the role of metalloproteases and their inhibitors in endometriosis development, MMP2, MMP3, MMP10, TIMP1, and TIMP2 expression was measured in healthy and eutopic endometrium, in OMA and DIE lesions." (PMID 32325785, 2020). "In accordance, previous study from our laboratory has found reduced interaction between TIMP-2 and MMP-2 during MMP-2 activation in mouse model of early endometriosis." (PMID 27695098, 2016). "It was previously reported that eutopic uterine endometrium from endometriosis patients had higher MMP-2 and lower TIMP-2 expression levels compared with normal fertile women." (PMID 23855590, 2013).
fibrosarcoma (8 papers, 2013 to 2021). A malignant mesenchymal fibroblastic neoplasm affecting the soft tissue and bone. "In this case, TIMP2-based protein LT actually served as the fibrosarcoma-oriented delivery carrier, and the integrated enediyne molecule acted as the highly potent effector agent." (PMID 29250984, 2018). "In the present study, intense and selective binding capability to human fibrosarcoma specimens was confirmed by tissue microarray, indicating the fibrosarcoma-oriented profile of the TIMP2-based protein." (PMID 29250984, 2018). "In response to irradiation both TIMP-1 and TIMP-2 protein levels were increased in cell lysates and to a higher extent in CM derived from irradiated fibrosarcoma cells when compared to cell lysates and CM derived from control cells." (PMID 23631818, 2013). "Therefore, a comprehensive understanding of the TIMP2-MMPs-substrate axis is crucial in directing potential mechanism-based therapeutic interventions against fibrosarcomas." (PMID 29250984, 2018). "As expected, a significant positive correlation was found between the secretion of u-PA and MMP-2 and a significant negative correlation between u-PA and TIMP-2 and between MMP-2 and TIMP-2 secretion by NM treatment of fibrosarcoma, chondrosarcoma and liposarcoma cells." (PMID 23661254, 2013). "In this in vitro study, the NM significantly inhibited secretion of u-PA and MMP-2 and/or -9 and increased secretion of TIMP-2 in fibrosarcoma, chondrosarcoma, liposarcoma and uterine leiomyosarcoma cells, suggesting its potential in modulating cancer invasion and metastasis." (PMID 23661254, 2013). "With a highly potent invasive potential, the fibrosarcoma HT1080 cells exhibit aberrant secretion of MMP-2 and MMP-14, which acts as the receptor of TIMP2; accordingly, this may be the mechanistic basis for selective intense binding of the TIMP2-based protein LT to fibrosarcomas." (PMID 29250984, 2018). "Considering the fact that several members of the MMP family are highly expressed in fibrosarcoma cells and TIMP2 may show specific interaction with MMPs, it is important to explore antitumor activity of the protein LT and its reconstituted analog LTE against fibrosarcoma." (PMID 29250984, 2018). "Taken together, these data provide evidence that the TIMP2-based recombinant protein LT endowed with binding capability to fibrosarcoma cells could serve as the carrier of targeting delivery, in addition, the enediyne-integrated analog LTE could act as a targeted agent." (PMID 29250984, 2018). "In the current study, a TIMP2-based recombinant protein LT and its enediyne-integrated analog LTE were prepared; furthermore, the fibrosarcoma-binding intensity and antitumor activity were investigated." (PMID 29250984, 2018). "Therefore, TIMP2 may play an active role in the development of fibrosarcoma-targeting agents." (PMID 29250984, 2018). "Mice with fibrosarcoma treated with CXCL10 combined with hypothermia presented reduced tumor burden and MVD, whereas the MMP2-inhibitor TIMP2, have been recently described as important prognostic factors in acute lymphoblastic leukemia." (PMID 26099922, 2015). "Next, we assessed protein levels of TIMP-1 and TIMP-2 in cell lysates and CM derived from the HT1080 fibrosarcoma cells, which were treated with IR and patupilone." (PMID 23631818, 2013). "Moreover, in TPA-induced HT-1080 fibrosarcoma cells, XN suppressed both the activation and expression of MMP-9 and MMP-2, reduced the MT1MMP mRNA level, and induced a substantial TIMP-1 and TIMP-2 depletion." (PMID 34204745, 2021). "Considering the fact that members of the MMP family might play a critical role in tumor progression and metastasis, TIMP2 was further investigated for the potential efficacy on fibrosarcoma and related soft tissue malignancies." (PMID 29250984, 2018). "mRNA expression of TIMPs in matrix embedded fibrosarcoma cells demonstrates that cell-density significantly increased TIMP3 and TIMP4 expression but did not impact TIMP1 or TIMP2." (PMID 30220965, 2018).
myocardial infarction (8 papers, 2013 to 2025). Gross necrosis of the myocardium, as a result of interruption of the blood supply to the area, as in coronary thrombosis. "The Castellano study focused on hippocampal aging, but TIMP2 deficiency has also been shown to inhibit cardiac remodeling processes after myocardial infarction in mice via inhibition of membrane type 1 matrix metalloproteinase (MT1-MMP)." (PMID 36077021, 2022). "Deficiencies in TIMP-2 activity after myocardial infarction accelerates adverse myocardial remodeling due to enhanced MMP-14 activity." (PMID 23349729, 2013). "Exosomes derived from human UC-MSCs that overexpressed TIMP2 enhanced cardiac function and promoted angiogenesis at the myocardial infarction site on a myocardial infarction rat model." (PMID 37434264, 2023).